DNPEP (aspartyl aminopeptidase)
Description:
Aminopeptidase with specificity towards an acidic amino acid at the N-terminus. Likely to play an important role in intracellular protein and peptide metabolism.
Synonyms: ASPEP; DAP
Tractability: Small molecule: a drug acting on it is in phase 2 or 3 trials; a structure with a bound ligand is known; it has a high-quality binding pocket; it belongs to a druggable protein family. PROTAC: ubiquitination databases record sites on it; its protein half-life has been measured; a small molecule that binds it is known.
Target class: Metallo protease MH clan; Protease; Metallo protease M18 family; Enzyme; Metallo protease
Gene: Protein-coding gene on chromosome 2 (219,372,029 to 219,400,022, reverse strand). Ensembl gene ENSG00000123992.
Subcellular location: Cytoplasm
Subcellular location (Human Protein Atlas): Cytosol
Gene Ontology:
Molecular function: identical protein binding; protein binding; aminopeptidase activity; zinc ion binding
Biological process: peptide metabolic process; proteolysis
Cellular component: blood microparticle; cytosol; nucleus; cytoplasm
Genetic constraint (gnomAD): Loss-of-function variants: 46 observed, 61.09 expected, observed/expected ratio (o/e) 0.75, 90% interval 0.59 to 0.96. The upper end of that interval is the gene's LOEUF score, 0.96, which puts it in group 4 of 6, group 1 being the genes least tolerant of losing a copy. Missense variants: 617 observed, 662.98 expected, observed/expected ratio (o/e) 0.93, 90% interval 0.87 to 1. Synonymous variants: 229 observed, 246.62 expected, observed/expected ratio (o/e) 0.93, 90% interval 0.83 to 1.04.
Homologues: Orthologues: chimpanzee DNPEP (97% identical), macaque DNPEP (97% identical), dog DNPEP (91% identical), pig DNPEP (89% identical), rabbit DNPEP (89% identical), guinea pig DNPEP (88% identical), rat Dnpep (88% identical), mouse Dnpep (88% identical), tropical clawed frog dnpep (70% identical), zebrafish dnpep (67% identical).
Diseases named in the same sentence as DNPEP in open-access papers:
DNPEP is named in the same sentence as 4 diseases in open-access papers, as found by Europe PMC text mining. Sharing a sentence is not in itself a finding about the gene and the disease. The quoted sentences say what the papers report.
breast carcinoma (4 papers, 2020 to 2023). "DNPEP (aspartyl aminopeptidase) expression is frequently downregulated in breast cancer tissues and regarded as tumor suppressor in vitro and in vivo breast cancer models." (PMID 36354672, 2022). "Finally, USP4 was reported to interact with and be degraded by aspartyl aminopeptidase (DNPEP), a metalloenzyme belonging to the M18 aminopeptidase family, resulting in suppression of its oncogenic role in breast cancer." (PMID 33681193, 2021). "This study reveals a non-canonical function of the E3 ubiquitin ligase FBXO3 in PI3K-induced breast cancer metastasis, showing that FBXO3 binds to and protects USP4 from aspartyl aminopeptidase (DNPEP)-mediated degradation, resulting in Twist1 protein stabilization and increased tumor metastasis." (PMID 38134227, 2023).
DNPEP also shares sentences with these, for which no sentence is quoted: tumor (2 papers); atherosclerosis (1); fibromyalgia (1).